KIRREL3 (kirre like nephrin family adhesion molecule 3)
Description:
Synaptic adhesion molecule required for the formation of target-specific synapses. Required for formation of target-specific synapses at hippocampal mossy fiber synapses. Required for formation of mossy fiber filopodia, the synaptic structures connecting dentate granule and GABA neurons. Probably acts as a homophilic adhesion molecule that promotes trans-cellular interactions and stabilize mossy fiber filipodia contact and subsequent synapse formation. Required for the coalescence of vomeronasal sensory neuron axons. May be involved in the hematopoietic supportive capacity of stroma cells; the secreted extracellular domain is directly responsible for supporting hematopoietic stem cells.
Synonyms: KIAA1867; NEPH2; KIRRE; MRD4; PRO4502
Tractability: Antibody: UniProt places it where antibodies can reach, with high confidence; its Gene Ontology location is reachable by antibodies, with high confidence; UniProt predicts a signal peptide or a membrane-spanning region. PROTAC: its protein half-life has been measured.
Gene: Protein-coding gene on chromosome 11 (126,423,358 to 127,003,460, reverse strand). Ensembl gene ENSG00000149571.
Subcellular location: Cell membrane; Secreted (Processed kin of IRRE-like protein 3)
Pathways (Reactome):
Cell-Cell communication: Nephrin family interactions
Gene Ontology:
Molecular function: protein binding; cell adhesion molecule binding
Biological process: cell-cell adhesion; hemopoiesis; hippocampus development; homophilic cell-cell adhesion; synapse assembly
Cellular component: plasma membrane; synaptic vesicle; axon; cell-cell junction; dendrite; extracellular region; membrane
Genetic constraint (gnomAD): Loss-of-function variants: 35 observed, 68.65 expected, observed/expected ratio (o/e) 0.51, 90% interval 0.39 to 0.68. The upper end of that interval is the gene's LOEUF score, 0.68, which puts it in group 2 of 6, group 1 being the genes least tolerant of losing a copy. Missense variants: 838 observed, 974.69 expected, observed/expected ratio (o/e) 0.86, 90% interval 0.81 to 0.91. Synonymous variants: 439 observed, 413.33 expected, observed/expected ratio (o/e) 1.06, 90% interval 0.98 to 1.15.
Gene-disease validity (ClinGen):
ClinGen rates the evidence that KIRREL3 causes each of these diseases.
complex neurodevelopmental disorder (autosomal dominant): Disputed. A disorder that involves more than one phenotype associated with the central nervous system, including but not limited to intellectual disability, autism, and seizures (epilepsy).
Homologues: Orthologues: macaque KIRREL3 (99% identical), chimpanzee KIRREL3 (98% identical), rat Kirrel3 (98% identical), dog KIRREL3 (97% identical), rabbit KIRREL3 (97% identical), mouse Kirrel3 (96% identical), guinea pig KIRREL3 (95% identical), pig KIRREL3 (95% identical), tropical clawed frog kirrel3 (84% identical), zebrafish kirrel3a (73% identical), zebrafish KIRREL3 (54% identical), Drosophila melanogaster kirre (28% identical), and 5 more. Paralogues in human: KIRREL1 (44% identical), KIRREL2 (33% identical), NPHS1 (22% identical).
Diseases named in the same sentence as KIRREL3 in open-access papers:
KIRREL3 is named in the same sentence as 27 diseases in open-access papers, as found by Europe PMC text mining. Sharing a sentence is not in itself a finding about the gene and the disease. The quoted sentences say what the papers report.
Intellectual disability (13 papers, 2015 to 2025). "The synaptic adhesion molecule KIRREL3 regulates synapse development in mice and is implicated in human neurological disorders, including autism spectrum disorder, intellectual disability, and Jacobsen syndrome (chromosome 11q deletion syndrome)." (PMID 41059509, 2025). "Among these, KIRREL3 is known to play a role in CNS development, and his variants have recently been related to intellectual disability, autism spectrum disorder, childhood apraxia of speech, cerebellar hypoplasia and mild dysmorphic features." (PMID 37605258, 2023). "In this study, we describe a young Caucasian boy with mild intellectual disability, cerebellar anomalies (cerebellar hypoplasia and mega cisterna magna) and minor dysmorphic features associated to a novel KIRREL3 variant." (PMID 37605258, 2023). "Alterations of KIRREL3 have been linked to neurodevelopmental disorders such as intellectual disability, autism spectrum disorder, and bipolar disorder." (PMID 35879288, 2022). "In humans, loss of the KIRREL3 gene was associated with neurodevelopmental disorders, such as Jacobson’s syndrome, intellectual disability, and autism spectrum disorder." (PMID 35928279, 2022). "Recently, genetic studies have revealed that genetic mutations in Kin of Irregular Chiasm-like 3 (KIRREL3) are associated with neurodevelopmental disorders, including intellectual disability and ASD in humans." (PMID 29362445, 2018). "This is consistent with prior publications associating non‐synonymous KIRREL3 variants with intellectual disability." (PMID 29271092, 2018). "Evidence of intellectual disability was noted in all six children with KIRREL3 variants, with scores below 70 on the cognitive assessment as compared to 61% of the total study group (p = .06)." (PMID 29271092, 2018). "Point mutations, copy number variations, and deletions in Kirrel3 have been repeatedly identified in patients with intellectual disability, autism spectrum disorders, and Jacobsen’s syndrome." (PMID 28670619, 2017). "In humans, copy number variations and exonic point mutations in the Kirrel3 gene are associated with intellectual disability, autism, and Jacobsen's syndrome, a rare developmental disorder that often includes intellectual disabilities." (PMID 26575286, 2015). "Neph2, also known as Kirrel3, is an immunoglobulin superfamily adhesion molecule implicated in intellectual disability, neurocognitive delay associated with Jacobsen syndrome, and autism spectrum disorders." (PMID 26283919, 2015). "Kirrel3 variants may be risk factors for autism spectrum disorder and intellectual disabilities in humans and we wondered whether identified disease-associated variants are located in specific exons or protein coding domains." (PMID 37977826, 2023). "Mutations of Kirrel3 have been associated with intellectual disability and autism." (PMID 37094040, 2023). "Kirrel3 is a cell-adhesion molecule that instructs the formation of specific synapses during brain development in mouse and Kirrel3 variants may be risk factors for autism and intellectual disabilities in humans." (PMID 37977826, 2023). "Children with KIRREL3 variants more often had minor facial dysmorphism and intellectual disability." (PMID 29271092, 2018). "Evidence of intellectual disability was noted in all six children with KIRREL3 variants in our study population, suggesting KIRREL3 dysfunction may be associated with a more severe pattern of deficits in children with ASD." (PMID 29271092, 2018). "Point mutations and deletions in the gene Kirrel3 are associated with neurodevelopmental disorders including autism, intellectual disability and Jacobsen’s syndrome, a chromosomal disorder that frequently includes epilepsy, autism, and intellectual disability." (PMID 28670619, 2017).
Intellectual disability (continued). "Recently dysfunction of KIRREL3, a synaptic molecule of the immunoglobulin superfamily, has been implicated in several neurodevelopmental conditions including intellectual disability, autism spectrum disorder, and in the neurocognitive delay associated with Jacobsen syndrome." (PMID 25902260, 2015). "Given the association between Kirrel3 mutations and intellectual disabilities, we investigated the role of Kirrel3 in hippocampal circuits, which are critical for learning and memory, and may be impaired in patients with intellectual disabilities." (PMID 26575286, 2015). "Alterations in the Kirrel3 gene are repeatedly associated with intellectual disabilities, but the role of Kirrel3 at synapses remained largely unknown." (PMID 26575286, 2015). "Given that alterations in the Kirrel3 gene are associated with autism and intellectual disabilities, this work provides the first insight into cellular mechanisms that may underlie Kirrel3-dependent neurological disorders." (PMID 26575286, 2015). "Recently, genetic links have been reported between mutations in the KIRREL3 gene and increased risk of neurodevelopmental disorders, including autism spectrum disorder (ASD) and intellectual disability." (PMID 29362445, 2018). "Mutations in CASK are known to result in microcephaly with pontocerebellar hypoplasia and severe intellectual disability, further evidence that KIRREL3 and CASK play a critical role in neurodevelopment." (PMID 29271092, 2018). "Mice lacking the intellectual disability and autism-associated gene Kirrel3 have an excitation-inhibition imbalance in the hippocampus but the precise synaptic changes underlying this functional defect are unknown." (PMID 28670619, 2017). "Importantly, in case of NEPH2/KIRREL3 gene in human chromosome 11q24.2, point mutations and chromosomal abnormalities were identified in autism spectrum disorders, intellectual disability and Jacobsen syndrome characterized by neurocognitive delay, suggesting its important roles in brain." (PMID 28381988, 2017).
autism spectrum disorder (10 papers, 2015 to 2025). A spectrum of developmental disorders that includes autism, and Asperger syndrome. "Interestingly, both KIRREL3 and EXOC6B genes are also related to autism spectrum disorder (ASD), another cognitive disease with a young age of onset." (PMID 38854406, 2024).
autism (8 papers, 2015 to 2024). Persistent deficits in social interaction and communication and interaction as well as a markedly restricted repertoire of activity and interest as well as repetitive patterns of behavior. "Mutations in the gene that encodes a protein called Kirrel3 are associated with autism, Jacobsen's syndrome, and other disorders that affect intellectual ability in humans." (PMID 26575286, 2015). "Additional studies further suggested KIRREL3 as an intriguing candidate for autism and a potential risk gene for Alzheimer's disease." (PMID 25902260, 2015). "However, a family history of autism or psychiatric disease was commonly observed, supporting variable phenotype in those with KIRREL3 variants, and the likely role of other genetic and environmental factors in the development of ASD in these patients." (PMID 29271092, 2018). "Our analysis supports the role of several genes/loci associated with autism (e.g., NRXN1, ADNP, 22q11 deletion) and identified new truncating (e.g., GRIK2, ROBO1, NINL, and IMMP2L) or recessive deleterious variants (e.g., KIRREL3 and CNTNAP2) affecting autism-associated genes." (PMID 30675382, 2019). "However, while Kirrel3-deficient mice displayed certain sensory abnormalities such as autism-like and hyperactive behavior phenotypes, no ataxia was reported." (PMID 39715266, 2024).
Jacobsen syndrome (8 papers, 2013 to 2025). A multiple congenital anomaly/intellectual disability contiguous gene syndrome caused by partial deletion of the long arm of chromosome 11. "KIRREL3 was highly expressed in brain and kidney, and shown to be associated with mental retardation autosomal dominant type 4 and neurocognitive delay associated with Jacobsen Syndrome." (PMID 23667675, 2013). "An interstitial deletion of 11q-implicating the KIRREL3 gene in the neurocognitive delay observed in Jacobsen syndrome has recently been reported." (PMID 25902260, 2015).
cognitive disorder (4 papers, 2015 to 2024). A disease affects cognitive processes. "The loss of KIRREL3 leads to changed axon organization, as well as male-male aggression and cognitive impairment, in mice." (PMID 38854406, 2024). "Subsequently, several independent studies also linked defects in KIRREL3 to neurological and cognitive disorders." (PMID 25902260, 2015). "Several of the identified interacting partners of KIRREL3, including MAP1B and MYO16, have previously been linked to neurological and cognitive disorders." (PMID 25902260, 2015).
Anxiety (2 papers, 2015 to 2018). Intense feelings of nervousness, tension, or panic often arise in response to interpersonal stresses. "In addition, Kirrel3−/− mice also showed normal anxiety-related behaviours and spatial or fear learning/memory." (PMID 29362445, 2018). "Anxiety-related behaviours and spatial or fear memory acquisition were normal in Kirrel3−/− mice." (PMID 29362445, 2018).
behavioral disorders (1 paper, 2015). "Altogether, our study provides valuable information for understanding KIRREL3 involvement in cognitive and behavioral disorders and provides further insights into molecular mechanisms of its action, in particular its potential involvement in synaptic actin-cytoskeleton through MYO16-WAVE1 complex." (PMID 25902260, 2015).
breast carcinoma (1 paper, 2025). "Recent studies have reported a highly significant association between the KIRREL3 region and breast cancer." (PMID 41149035, 2025).
dementia (1 paper, 2024). Loss of intellectual abilities interfering with an individual's social and occupational functions. "Again, among their counterpart genotype carriers (KIRREL3 rs4144611 GG + TG or rs580382 TT + CT carriers and EXOC6B rs61619102 GG + GC carriers), there were no such relationships between CD34+CD133+ quartiles and AD or all-cause dementia risk." (PMID 38854406, 2024).
diabetes (1 paper, 2023). "The A-allele in the KIRREL3-rs4935985 variant was associated with higher UACR and risk of microalbuminuria and kidney damage in participants with diabetes, but a lower risk of microalbuminuria in the absence of diabetes." (PMID 37446387, 2023). "The KIRREL3-rs4935985-A variant predicted higher UACR and risk of microalbuminuria and kidney damage in participants with diabetes, whereas it predicted a lower risk of microalbuminuria in the absence of diabetes." (PMID 37446387, 2023).
Huntington disease (1 paper, 2019). Huntington disease (HD) is a rare neurodegenerative disorder of the central nervous system characterized by unwanted choreatic movements, behavioral and psychiatric disturbances and dementia. "Among the upregulated DEGs, Zfp97 (logFC = 0.7) is also upregulated in Huntington’s disease and Kirrel3 (logFC = 0.3) has been suggested as a potential risk gene for AD." (PMID 30283031, 2019).
RASopathy (1 paper, 2017). Developmental syndromes caused by germline mutations (or in rare cases by somatic mosaicism) in genes that alter the Ras subfamily and mitogen-activated protein kinases that control signal transduction. "In addition, two other noteworthy loci (one between KIRREL3 and ETS1, the other between GATA3 and CELF2) overlap between top results from ASD epistasis and RASopathy modifier mapping and contain genes of particular interest." (PMID 28076348, 2017).
neurodevelopmental disorder (11 papers, 2012 to 2024). A behavioral and cognitive disorder with onset during the developmental period that involves impaired or aberrant development of intellectual, motor, or social functions. "In particular, Kirrel3 regulates the output specificity of hippocampal DG axons, and disruption of its locus has been associated with neurodevelopmental disorders." (PMID 31386671, 2019). "Recently, disruption in the KIRREL3 locus (28 copy number variants) was identified in patients with ASD or neurodevelopmental disorders by sequencing chromosomal abnormalities." (PMID 29362445, 2018). "To elucidate the causal relationship between KIRREL3 deficiency and behavioural abnormalities relevant to neurodevelopmental disorders, we generated global Kirrel3-knockout (Kirrel3−/−) mice and investigated the detailed behavioural phenotypes." (PMID 29362445, 2018). "Given these associations with neurodevelopmental disorders affecting learning and memory, the role of Kirrel3 in the mouse hippocampus was recently investigated." (PMID 28670619, 2017). "Kirrel3 is an important molecule for synapse and circuit formation with gene variants that are associated with neurodevelopmental disorders, yet Kirrel3 function remains largely unknown." (PMID 37977826, 2023). "Altered E/I ratios are hypothesized to underlie neurodevelopmental disorders, and our work suggests this may be an important circuit defect of Kirrel3-associated diseases." (PMID 26575286, 2015). "Thus, Kirrel3 may also regulate formation of other specific types of synapses throughout the brain, which may further contribute to its association with neurodevelopmental disorders." (PMID 26575286, 2015). "Variants in KIRREL3 and ZFHX3 have recently been associated with ASD and neurodevelopmental disorders, respectively, so it will be interesting to determine how these genes regulate fate of MGE-derived cells in the future." (PMID 38419656, 2024). "Disruption of KIRREL3 has been reported in patients with neurodevelopmental disorders, and de novo mutations have been found in whole genome analysis of twins with ASD." (PMID 29271092, 2018). "In a second patient with a neurodevelopmental disorder and a t(X;11) translocation, the breakpoint, located 39 kb upstream of the KIRREL3 coding region, altered both mRNA and protein levels." (PMID 25902260, 2015). "Our findings demonstrate that subtle synaptic changes during development impact circuit function and provide the first insight toward understanding the cellular basis of Kirrel3-dependent neurodevelopmental disorders." (PMID 26575286, 2015). "In sum, the selective loss of MF filopodial synapses with GABA neurons likely underlies the hippocampal activity imbalance observed in Kirrel3 knockout mice and may impact neural function in patients with Kirrel3-dependent neurodevelopmental disorders." (PMID 28670619, 2017). "The synaptic changes we found in mice lacking Kirrel3 shed new light on how a defective Kirrel3 gene could cause neurodevelopmental disorders in humans." (PMID 28670619, 2017).
KIRREL3 also shares sentences with these, for which no sentence is quoted: brain disorder (2 papers); mental disorder (2); neurological disease (2); Obesity (2); Ataxia (1); bipolar disorder (1); cognitive delays (1); dyslexia (1); focal segmental glomerulosclerosis (1); hyperlipidemia (1); kidney damage (1); mental retardation autosomal dominant type 4 (1); microcephaly (1); neuromuscular disease (1).